IL1B (interleukin 1 beta)
Diseases named in the same sentence as IL1B in open-access papers (continued):
Sharing a sentence is not in itself a finding about the gene and the disease.
atopic dermatitis (67 papers, 2013 to 2026). "A pathological increase of cutaneous IL-1β is associated with edema formation, epidermal hyperproliferation, and contact atopic dermatitis in humans." (PMID 23997805, 2013). "These cytokines play a crucial role in the pathogenesis of atopic dermatitis; for example, increased IL-1β secretion following the activation of the MAPK and NF-κB pathways promotes the production of additional pro-inflammatory cytokines." (PMID 40563511, 2025). "Atopic dermatitis is characterized by the overproduction of pro-inflammatory cytokines (such as IL-1β, IL-6, IL-8)." (PMID 40563511, 2025). "The objective of this research was to investigate the concentrations of TSLP and IL-1β in children with atopic eczema, FA, and anaphylaxis to healthy controls, assessing their potential as biomarkers for allergic conditions." (PMID 39860604, 2025). "The NLRP3 inflammasome facilitations the maturation of interleukin (IL)-1β, a proinflammatory cytokine that is critically involved in the pathogenesis of atopic dermatitis (AD)." (PMID 37175425, 2023). "In a recent study, IL-1β and IL-8 were found to be highly expressed cytokines in the stratum corneum of atopic dermatitis lesional skin." (PMID 34834790, 2021). "The exotoxin α-toxin from Staphylococcus aureus (S. aureus) induced IL-1β secretion mediated by caspase-1 activation in monocytes from healthy controls, and IL-1β secretion by α-toxin was impaired in monocytes from atopic dermatitis patients." (PMID 33534121, 2021). "Research has also shown that U. rhynchophylla relieves atopic dermatitis and the indole alkaloids of U. rhynchophylla have anti-inflammatory mediators such as IL-1β, NO, and TNF-α." (PMID 31116257, 2019). "They reported that treatment of atopic dermatitis mouse model with ZnO NPs suppresses local inflammation by down-regulation of the expression levels of pro-inflammatory cytokines such as IL-1β, IL-6, and TNF-α." (PMID 30127816, 2018). "In the sensitization and elicitation phase of allergic dermatitis, IL-1β and TNF-α play a pivotal role." (PMID 29029618, 2017). "Although no significant variations in genotype frequencies were detected for IL-1β rs16944, significant associations were observed for TSLP rs2289277, particularly with conditions such as atopic dermatitis, food allergy, anaphylaxis, and combinations of these diseases." (PMID 39860604, 2025). "Studies using filaggrin-mutant mice demonstrate that IL-1β production is significantly elevated in inflamed skin and that blocking IL-1β signaling reduces inflammation, suggesting its critical importance in the pathogenesis of atopic dermatitis." (PMID 41304926, 2025). "In atopic dermatitis-like skin lesions, laminarin alleviates inflammation and modulates immune responses by suppressing IgE hyperproduction, mast cell infiltration, and the release of pro-inflammatory cytokines such as IL-1β, TNF-α, MCP-1, and MIP-1α." (PMID 41303564, 2025). "Sleep disturbances in atopic dermatitis are not only due to sleep deprivation related to nighttime itching but also to dysregulation in the release of inflammatory mediators (IL-1b, IL-2, TNF-a, IFN-g, IL-6, IL-4, and IL-10) and neuroendocrine molecules such as cortisol and melatonin." (PMID 38731996, 2024). "Interestingly, the immunoproteasome inhibitor PKS3053 prevented the induction of several IFN-regulated genes and the pro-inflammatory cytokines TNF and IL-1β to tape stripping in a mouse model for atopic dermatitis." (PMID 36591277, 2022). "Therefore, our results suggest that M. concanensis exerts anti-atopic dermatitis effects by inhibiting the NLRP3 inflammasome-mediated IL-1β." (PMID 36297328, 2022). "Whereas the induction of TSLP by IL1β is best established in human and murine keratinocytes in atopic dermatitis, other cell types including immune cells may substantially contribute to TSLP production." (PMID 32285594, 2020).
atopic dermatitis (continued). "Expression responses to IL-1B and IL-36 were additionally correlated with transcriptional alterations observed in other skin diseases, such as atopic dermatitis (rs = 0.291), eczema (rs = 0.283), and allergic dermatitis (rs = 0.269)." (PMID 29434599, 2018). "IL-1β plays a central role in innate immunity and has been shown to induce urticarial rashes in autoinflammatory diseases and play a role in bronchial asthma, contact hypersensitivity and atopic dermatitis." (PMID 24983946, 2014). "We hypothesized that overexpression of IL32 in hair follicle keratinocytes of patients with atopic dermatitis would lead to the excessive production of pro-IL1β and that the activation of IL1β from pro-IL1β by inflammasome complex, in which NLRP2 protein might be involved, would be augmented." (PMID 23385231, 2013). "The results showed that CSSH reduced pro-inflammatory cytokines (IL-1β, IL-6, IL-8, MCP-1 and CXCL10) and atopic dermatitis-related cytokines (IL-4, CCL17, MDC and RANTES) in TNF-α/IFN-γ-induced HaCaT cells." (PMID 38931136, 2024). "Among the isolated compounds, compounds 2–5, 7, 9, and 10 showed inhibitory effects on inflammatory cytokines (IL-1β, IL-6, and TNF-α) related to atopic dermatitis against TNF-α/IFN-γ-stimulated HaCaT keratinocytes at 10 μM." (PMID 39519643, 2024). "According to previous studies, epithelial cells and keratinocytes damaged by atopic dermatitis produce proinflammatory cytokines (such as TNF-α, IL-1β, IL-6, and IL-8) and chemokines (such as CCL17/TARC, CCL22/MDC)." (PMID 36793948, 2023). "In atopic dermatitis, damaged epithelial cells and keratinocytes produce proinflammatory cytokines and chemokines such as TNF-α, IL-1β, IL-6, IL-8, CCL17, and CCL22." (PMID 36158872, 2022). "Additionally, NLRP2 and IL-1β expression was more upregulated in human hair follicle-derived keratinocytes from atopic dermatitis patients than controls and it would be of interest to further explore whether the NLRP2 inflammasome plays a role in atopic dermatitis-associated inflammation." (PMID 33925158, 2021). "Second, for the treatment of atopic dermatitis, C. asiatica significantly reduced the inflammation response (TNF-α ↓, IL-1β ↓, IL-8 ↓, IL-4 ↓, and IL-13 ↓), and also the local immune response (IgE ↓)." (PMID 33013406, 2020). "Importantly, in an atopic dermatitis-like cell model induced by TNFα/IFNγ, LF216EV significantly modulated the expression of immune regulatory genes (TSLP, TNFα, IL-6, IL-1β, and MDC), indicating its potential functionality in atopic dermatitis." (PMID 40028723, 2025). "Our findings are in line with other preclinical studies beyond atopic dermatitis wherein HSP90 inhibition exerted anti-inflammatory effects by targeting several inflammatory cytokines (e.g. TNF, IL-1β, and IL-6) and signalling pathways (e.g. ERK1/2, p38, and JNKs)." (PMID 38274815, 2023). "Dermatophagoides pteronyssinus, a house dust mite allergen, is an important etiology for the development of atopic dermatitis and induces assembly of the NLRP3 inflammasome complex resulting in caspase-1 activation and IL-1β and IL-18 release from keratinocytes." (PMID 33534121, 2021). "Astragalin is associated with various pharmacological and biological activities, including anti-inflammatory, antioxidant activity, anti-atopic dermatitis activity, TNF-a, IL-1b, and IL-6 production inhibiting activity, and inhibiting histamine release in human blood cells." (PMID 33968110, 2021). "Interestingly, OSB emissions significantly reduced the release of CCL2 from TCS‐stimulated and unstimulated keratinocytes and slightly reduced IL‐1β from TCS‐stimulated keratinocytes, confirming no or rather beneficial effects of OSB‐specific VOCs in a human in vitro atopic dermatitis model." (PMID 40114338, 2025). "Notably, astersaponin J exhibited a dose-dependent reduction in IL-1β, IL-6, and TNF-α levels, suggesting that it could be a potential candidate of a therapeutic agent for atopic dermatitis." (PMID 39519643, 2024).
atopic dermatitis (continued). "A recent study has shown that, in animal models of atopic dermatitis, atopic dermatitis-like symptoms were further improved by inhibiting HMGB1 expression in mast cells, preventing NF-κB nuclear translocation, and reducing the release of cytokines such as TNF-α and IL-1β." (PMID 34007295, 2021).
fungal infections (67 papers, 2010 to 2025). "For example, the IL1B rs16944 polymorphism is associated with susceptibility to different infections, including invasive fungal infections and tuberculosis." (PMID 41087719, 2025). "In terms of human genetic evidence, several polymorphisms in the Nlrp3 gene have been shown to influence susceptibility and severity of fungal infections by modulating inflammasome activation and IL-1β production." (PMID 41249509, 2025). "The results of studies indicate that IL15, FLT3L, CXCL10, and IL1B, which demonstrated the most promising outcomes among the estimates, are actually associated with numerous viral, bacterial, parasitic, and fungal infections." (PMID 40650062, 2025). "The signalling axis of β-glucan, DECTIN-1, SYK and CARD9 is a central pillar of inflammasome activation, as well as the release of inflammasome/pyroptosis-associated IL-1β and IL-18 in fungal infection and beyond." (PMID 38515333, 2024). "The critical role of IL-1β in controlling C. neoformans and other pathogenic fungal infections through the activation of the NLRP3 inflammasome has recently been documented (46, –, 48)." (PMID 27165801, 2016). "In preclinical models, anakinra was effective in diminishing IL-1β production and mitigating inflammation in patients with cystic fibrosis and chronic granulomatous disease, which have an increased risk for fungal infections and the activation of inflammasomes." (PMID 41304803, 2025). "Although IL-1β plays an active role in containing infection caused by different fungi, its role in controlling fungal infections remains unclear." (PMID 27434108, 2016). "The specific mechanisms involved remain unknown, but there appears to be a role played by the fungal infection itself, as genetic variants that reduce the production of IL-1β have been shown to contribute to susceptibility to invasive fungal infections following solid-organ transplantation." (PMID 38651925, 2024). "Given the impact of heightened IL-1β signaling in the context of fungal infections, there is interest in the synergistic application of antifungal agents alongside targeted immunomodulatory therapies." (PMID 41304803, 2025). "Immediately after systemic infection with C. albicans, the expression of IL-1α, IL-1β, and IL-1R is rapidly upregulated in the kidneys, possibly suggesting a role in the host defense against fungal infection." (PMID 40097388, 2025). "Signaling through inflammasome-dependent IL-1 cytokines (IL-1β and IL-18) is protective in invasive fungal infections." (PMID 41249509, 2025). "Although the term “trained innate immunity” was first proposed in 2011, protective activity against lethal bacterial and fungal infections following pretreatment with IL-1β was reported as early as 1984." (PMID 41087719, 2025). "Th1-associated cytokines, such as IL-1β, IL-2, IFN-γ, and TNF-α, play crucial roles in macrophage recruitment, activation, and the generation of reactive oxygen species to combat fungal infections while promoting CD4+ T-cell responses." (PMID 41425969, 2025). "IL-1β is involved in protecting against bacterial and fungal infections, particularly in mucosal tissues, by regulating IL-17 production." (PMID 38032288, 2023). "Nevertheless, secretion of IL‐1β during fungal infections involves collaboration between NLRP3 and CLRs since the SYK‐CARD9 pathway is required for the production of pro‐IL‐1β, and for the activation step of the inflammasome following its assembly." (PMID 36114607, 2023). "Further, a significant variation in IL-17A, TNF-β, IL-1β, IL-2, IL-4, IL-6, IL-8, IL-10, IL-22, and IL-12p70, between the uninfected group and the pulmonary bacterial and fungal infection group (P < 0.05) was observed." (PMID 36319826, 2022). "Neutrophils play major roles against bacteria and fungi infections not only due to their microbicide properties but also because they release mediators like Interleukin-1 beta (IL-1β) that contribute to orchestrate the inflammatory response." (PMID 36091026, 2022).
fungal infections (continued). "IL-17A mediates host resistance to extracellular bacterial and fungal infections by acting as a powerful inducer of neutrophil growth factors, such as granulocyte colony stimulating factor (G-CSF) and cytokines IL-1β, IL-9, and IL-12p70." (PMID 33919521, 2021). "We and others reported that neutrophils are an important source of IL-1β during bacterial and fungal infections." (PMID 34010648, 2021). "Here, the adaptor protein negatively regulates cytokine expression by fine-tuning pro-IL-1β expression in macrophages following bacterial infection, contrasting its role in fungal infection in which CARD9 primarily drives pro-inflammatory cytokine responses." (PMID 34209576, 2021). "For example, neutrophils are considered the principal source of proteinase 3, which processes IL-1β, during the acute bacterial and fungal infection." (PMID 33644037, 2020). "Of note, expression and secretion of TNF-α and IL-1β in NLC were strongly affected by ibrutinib mimicking fungal infection." (PMID 32983178, 2020). "The obvious risk related to MALT1 inhibition is thus susceptibility to infections, particularly to fungal infections due to the link between dectin, MALT1, IL-1β and IL-17." (PMID 32870913, 2020). "Caspase-1 and caspase-8 are required for IL-1β processing and secretion during this fungal infection." (PMID 31425553, 2019). "The quantification of IL-1β and TNFα in the corneas of the mice with fungal infection was determined by ELISA." (PMID 31285488, 2019). "IL-1β and other pro-inflammatory cytokines are produced early in response to fungal infections and promote phagocytosis and other means of innate immune response." (PMID 30946748, 2019). "During the middle-advanced stage of fungal infection, the IL-1β, IL-6, IL-8, and IFN-γ levels in the aqueous humor were significantly increased compared to non-keratitis controls." (PMID 29673332, 2018). "One of the main functions of NLRP3 is to participate in IL-1β maturation which is important in the host defense against Pneumocystis and other fungal infections." (PMID 29170665, 2017). "Our data identify a negative regulatory role for CARD9 on IL-1β production in bacterial infection that contrasts its role in fungal infections in which it drives proinflammatory responses." (PMID 27670879, 2016). "IL-1β is one of the most powerful pro-inflammatory cytokines and has been shown to be protective in several bacterial, viral and fungal infection models." (PMID 25684031, 2015). "We reported that TIR-8/SIGIRR is required for host resistance to fungal infections by reducing IL-1β–dependent activation of inflammatory Th17 responses." (PMID 25375146, 2014). "Pro-IL-1β was detected in the cell lysate using ELISA and was clearly produced in response to the fungal infection alone." (PMID 24340123, 2013). "Among these genes those related to host defense against fungal infection were upregulated between 2 and 6 hours of exposure to the fungus, such as IL-1β, IL-8, CXCL2, CCL4, CCL3, and CCL20, coinciding with an increase in phagocytosis." (PMID 23984400, 2013). "As expected, we found that IL-1β was up-regulated in wild-type mice in response to fungal infection." (PMID 22174673, 2011). "Protective immunity against fungal infections via TH-17 cellular responses requires the expression of IL-1β, IL-23 and IL-6 by DCs." (PMID 21283787, 2011). "Furthermore, we noticed that the levels of IL-1β, a cytokine related to the induction and maintenance of MDSCs in the context of fungal infection, were reduced after anti-Gr1 treatment." (PMID 36776848, 2023). "Overall the cytokine pattern observed in this study using long-term dexamethasone treatment and concomitant fungal infection, namely lowering of IL-1β, IL-6, and IL–8 and an increase in IL-10, implicates a shift from Th1 towards Th2, a pattern associated with suppressing antifungal properties." (PMID 33803702, 2021).